IL1B (interleukin 1 beta)
Diseases named in the same sentence as IL1B in open-access papers (continued):
Sharing a sentence is not in itself a finding about the gene and the disease.
breast cancer (continued). "No other significant differences were found between the different groups of breast cancer patients with respect to TNFα and IL-1β expression in the tumor cells (namely: IDC-no-relapse vs. DCIS; IDC-no-relapse vs. IDC-with-relapse)." (PMID 21486440, 2011). "Furthermore, we have identified two possible biomarkers (IL-1β and IL-6) for assessing the efficacy of anti-VEGF therapy in breast cancer patients." (PMID 19888452, 2009). "In addition, we found that changes in serum IL-1β and IL-6 levels correlated with response to therapy, identifying two possible biomarkers for assessing the effectiveness of anti-VEGF therapy in breast cancer patients." (PMID 19888452, 2009). "Polymorphisms within key interleukin genes (IL1A, IL1B, IL1RN, IL4R, IL6 and IL10 do not appear to play a significant overall role in breast cancer susceptibility or severity." (PMID 16842617, 2006). "Additionally, DOX-induced breast cancer cell-conditioned medium (D-CM) exhibits similar toxic effects as D-BCC-EXOs, as evidenced by comparable reductions in cell viability and increases in LDH, IL-1β, and IL-18 levels." (PMID 40360476, 2025). "This reduction in IL-1B, a pro-inflammatory cytokine involved in cancer progression, suggests that SUSD2 might influence inflammatory responses and tumor microenvironment dynamics in HER2+ breast cancer." (PMID 39791720, 2024). "In summary, although GSDMD expression was associated with survival and a decreased M2-type macrophage signature in patients with breast cancer, we did not observe a major impact of GSDMD deficiency in two different mouse cancer models, of which one is known to be IL-1β-dependent." (PMID 39224600, 2024). "TUBA1B+ TAMs, C1QC+ TAMs and VCAN+ TAMs were more prevalent in HER2+ breast cancer, whereas IL1B+ TAMs, SLC40A1+ TAMs and APOC1+ TAMs were more dominant in ER+ breast cancer, which illustrates the heterogeneity of TAM subtypes in various molecular subtypes of breast cancer." (PMID 39232806, 2024). "In addition, IL-1B from MDA-MB-231 cells activated mesenchymal stem cells, leading to the induction of CXCL-12, which, in turn, promoted the trans-endothelial migration of these breast cancer cells into the bone." (PMID 38800348, 2024). "For instance, it was demonstrated that CCL2/monocyte chemoattractant protein-1, CCL5, IL-1β, IL-6, tumor necrosis factor α, vascular endothelial growth factor, and leptin released by CAAs in the TME promote the proliferation, and dissemination of breast cancer cells." (PMID 36980280, 2023). "Furthermore, four other candidate genes SPARC, THY1, IL1B and CXCL8 are reported in this study as the key regulatory genes which can modulate co-regulatory between different clusters in the PPI network of the brain metastasis tumours from breast cancers." (PMID 35045088, 2022). "In addition, induction of HIF-1α protein by IL-1β and IGF-I has been reported in other cell lines, such as human osteoarthritic chondrocytes, cytotrophoblast cells, human gingival and synovial fibroblasts, and colon and breast cancer cells." (PMID 36497143, 2022). "Similarly, a recent study found a negative correlation between the pro-inflammatory cytokine, IL-1β, and depressive symptoms in patients with breast cancer with a mean age of 45 years." (PMID 35547250, 2022). "Studies on the role of IL-1β in promoting VM in breast cancer cells have not been well-characterized, which could help us explore and develop effective anti-cancer therapeutic strategies." (PMID 34055597, 2021). "Interestingly, the expression of cytokines in both types of breast cancer cell lines differed significantly e.g., ME significantly enhanced the expression of IL-1β and IL-6 genes in MCF-7 cells, whereas we did not observe such an effect in 4T1 cells." (PMID 34201348, 2021). "Next, this study investigated whether there is nonvesicular IL1β-mRNA in human breast cancer TCM because it was reported that human glioma stem cell culture contained mRNA in EVs and nonvesicular RNPs24." (PMID 34135341, 2021).
breast cancer (continued). "In the bone metastatic niche, microenvironmental IL-1β enhances the ability of breast CSCs to form colonies by activation of NF-κB and cAMP-response element-binding protein (CREB) signaling, Wnt ligand secretion, and autocrine Wnt signaling in breast cancer cells." (PMID 33123472, 2020). "TNF-α levels was significantly reduced in breast cancer patients that are chronically exposed to pesticides when compared to the unexposed ones (94.6 ± 8.52 pg/mL and 127.2 ± 13.99 pg/mL, respectively, p = 0.0443), while IL-1β was not different." (PMID 32984049, 2020). "For example, IL1β positively modulates TSLP production and secretion in DCs in vitro, and in a recent study, myeloid cells, including neutrophils and monocytes, have been shown to produce TSLP in response to IL1α, a mechanism that was responsible for breast cancer spreading." (PMID 32285594, 2020). "The analysis of tumor tissues from advanced-stage breast cancer patients demonstrated an increase in the likelihood of developing bone metastases in patients with IL-1β-positive primary tumors compared to patients with IL-1β-negative tumors." (PMID 33322216, 2020). "As IL-1β is not found to be expressed in homeostatic conditions, its elevated expression can be noticed in many types of solid tumors, such as colon cancer, breast cancer, or melanomas, and is known as the “gatekeeper” of inflammation." (PMID 33015196, 2020). "In addition, we cannot rule out that IL-1β and IL-23 mediate breast cancer progression through immune-regulatory functions." (PMID 32649314, 2020). "CAAs secrete more chemokine (C–C motif) ligand 2 (CCL2), chemokine (C–C motif) ligand 5 (CCL5), interleukin-1β (IL-1β), interleukin-6 (IL-6), tumor necrosis factor-alpha (TNF-α), vascular endothelial growth factor (VEGF), leptin, etc., which can promote the invasion and metastasis of breast cancer." (PMID 31500658, 2019). "However, controversial effects have been attributed to IL-1β and TNF-α in breast cancer." (PMID 31093512, 2019). "Remarkably, we found that multiple genes that belong to the NLRP3 inflammasome pathway, including P2rx7, Nlrp3, Casp1, Il1a and Il1b are upregulated in CAFs isolated from mammary carcinoma, but not in normal mammary tissue, or in fibroblasts isolated from mammary hyperplasia." (PMID 31558756, 2019). "DHA-treated breast cancer cells triggered increased caspase-1and gasdermin D activation, enhanced IL-1β secretion, translocated HMGB1 towards the cytoplasm, and membrane pore formation when compared to untreated cells, suggesting DHA induces pyroptosis programmed cell death in breast cancer cells." (PMID 29386662, 2018). "Besides, upon treatment with IL-1β, expression level of IL-1β was greatly enhanced in UC-MSCs, but not in breast cancer cells, implying a positive feedback loop in MSCs." (PMID 29670904, 2018). "Furthermore, either MGDAs co-culture or treatment of β-hydroxybutyrate, an intrinsic histone deacetylase (HDAC) inhibitor, increases histone H3K9 acetylation and induces expressions of IL-1β and LCN2 to enhance tumorigenicity in MCT2-expressing breast cancer cells." (PMID 28281525, 2017). "IL-1β indirectly induces motility in cancer cells through mesenchymal stem cells (MSC)-dependent release of chemokines such as CXCL1, 2, 3, 5, 6, 8, CCL2, 3, 5, and 20 suggesting correlation between interaction of these cells and the metastatic potential of the breast cancer cells." (PMID 28609459, 2017). "In breast cancer cells, TG2 overexpression conferred EMT and stem-cell-like phenotypes, and IL-1β treatment increased stem-cell-like phenotypes, invasion, and estrogen-independent tumor growth in a TG2-dependent manner, which was attenuated by either anti-IL-6 or anti-IL-1β antibody treatment." (PMID 27609180, 2016).
breast cancer (continued). "Withdrawal of clinically relevant doses of anakinra (1mg/kg/day) used in the current study is not reported to induce a spike in circulating IL-1B, indicating that this dose may be more effective for treating breast cancer metastasis." (PMID 27765923, 2016). "Thus, the effect of IL-1β on TG2-overexpressing luminal-type breast cancer cells, which do not normally express TG2 or IL-6, was evaluated." (PMID 27609180, 2016). "Therefore, IL-1β in the tumor microenvironment and tumor cell expression of TG2 may be potential targets for combating resistance in luminal-type breast cancer cells." (PMID 27609180, 2016). "In two patients with benign ovarian disease and a family history of ovarian and/or breast cancer, average urinary IL-1β levels were three times higher (0.99 pg/ml) compared to patients with benign ovarian disease, but without a family history of ovarian and/or breast cancer (0.33 pg/ml)." (PMID 25403235, 2014). "One of the important observations in our study was the recognition of inflammation related factors in the IPA network and a number of pathway showed IL-5, IL-1β, TNF, IL-4, and INFγ as the central molecules highlighting an already existing relationship between inflammation and breast cancer." (PMID 23216862, 2012). "Moreover, IFN-γ, IL-1β, and TNF-α are key cytokines released by cytotoxic CD8+ TEff cells; in vitro exposure to IFN-γ, IL-1β, and TNF-α induced cellular elongation, migration, and invasion of ER– MDA-MB-231 breast cancer cells, which were limited by NOS/COX inhibitors." (PMID 40663402, 2025). "More specifically, IL-1β could directly promote epithelial–mesenchymal transition, stimulate tumor cell adhesion to endothelial cells, activate matrix metalloproteinase (MMP) secretion, and mediate related-malignancy signaling pathways, leading to pathological progression of breast cancers." (PMID 36823153, 2023). "Additionally, AFI has been reported to have anticancer activities against human breast cancer cells (MCF-7) and lung cancer cells (HCC827) by stimulating the production of tumor necrosis factor-alpha (TNF-α), interleukin-6 (IL-6), and interleukin-1 beta (IL-1β)." (PMID 36059847, 2022). "However, the effect of IL-1β on the VM of breast cancer has not been clearly elucidated." (PMID 34055597, 2021). "Moreover, IL-1β from macrophages or breast cancer cells themselves has been shown to induce the secretion of osteoprotegerin, a secreted member of the TNF receptor family involved in bone resorption, in breast cancer via the p38 and p42/22 MAPK signaling pathways." (PMID 33322216, 2020). "Indeed, IL-1β is considered as a master cytokine in the progression of breast cancer as its production has been found correlated with advanced diseases, whereas the IL1R1 inhibition by the antagonist anakinra was shown to prevent the growth of breast cancer and the bone metastasis in mouse models." (PMID 32778144, 2020). "Therefore, IL-1β in the tumor microenvironment and tumor cell TG2 and IL-6/STAT3 signaling pathway may be potential targets for combating recurrent and therapy-resistant luminal-type breast cancer." (PMID 27609180, 2016). "In search of the factors produced by metastatic cells that could enhance chemokine production by MSCs, we identified IL-1β as a potent NF-κB regulator that was produced at higher levels by the metastatic breast cancer cells compared to the non-metastatic cell lines." (PMID 26362269, 2015). "The tumor-promoting activities of the inflammatory mediators CCL2 & CCL5 and TNFα & IL-1β in breast cancer are not fully overlapping (references above), therefore their coordinated expression may eventually provide advantage to the developing and metastasizing tumor." (PMID 21486440, 2011). "For instance, IL-1β stimulation promotes the invasion of MCF-7, a non-metastatic breast cancer cell line, by inducing the expression of MMP9 in a dose-dependent manner." (PMID 39858071, 2025).
breast cancer (continued). "ICAM1 expression is exclusive to triple-negative and HER2-positive breast cancer but is induced by proinflammatory cytokines such as TNF–α, IFN–γ, and IL–1β, independent of the tumor hormone receptor status, and is linked to high immune cell infiltration." (PMID 39590296, 2024). "The results showed that higher expressions of IL1α and IL1β, but not IL8, are significantly correlated with shorter overall survival times for breast cancer patients." (PMID 37551997, 2023). "This inhibition has permitted as evidence the role of de-methylation of genomic DNA in IL-1β-induced tumor progression and bone metastasis in MCF-7 non-metastatic breast cancer cell lines." (PMID 36499741, 2022). "Overall, our data shows OPG can be induced across different breast cancer subtypes independent of basal OPG and IL1B secretion levels." (PMID 28143606, 2017). "Unlike inflammatory cells, IL-1β stimulation did not lead to IL-6 production, and the overexpression of TG2 alone did not lead to IL-6 production in luminal-type breast cancer cells." (PMID 27609180, 2016). "Significantly higher values of RANKL, CTKS, PTH1R, IL-6, IL-1β and MMP-1 were found in bone fragments cultured with MCF-7 breast cancer cells in comparison to bone fragments cultured without cancer cells, both in normoxic and hypoxic conditions." (PMID 27765913, 2016). "While studying the transcriptional regulation of iNOS in breast cancer cell lines, we noticed that in general lines such as MCF-7 express the enzyme in response to stimulation with a cytokine mix (Il1-β, IFN-γ and TNF-α) while others such as MDA-MB-231 do not." (PMID 26271992, 2015). "Next, we compared the three groups of breast cancer patients (DCIS, IDC-no-relapse, IDC-with-relapse) with respect to the incidence of expression of CCL2, CCL5, TNFα and IL-1β in the tumor cells." (PMID 21486440, 2011). "The result showed that IL-1β but not IFN-γ mRNA was highly expressed in M1 macrophages, suggesting that IL-1β may be an M1 macrophage cytokine involved in PIGR upregulation in breast cancer cells." (PMID 36207349, 2022). "However, they observed that, only WF of Luminal A breast cancer patients, but not that of the Luminal B subtype showed IORT-mediated increased IL-1β levels." (PMID 33946741, 2021). "Other cytokines such as IL-1β have been known to synergistically interact with OSM in the context of joint damage and synovial fibroblast-mediated inflammation; however, the exact nature of this interaction has not been studied in breast cancer." (PMID 31007849, 2019). "However, contrary to earlier reports in breast cancer, just no more than 2-fold increase following TNF-α or IL1β treatment." (PMID 28412955, 2017). "However, as IL-1β silencing in MDA-MB-231 cells does not completely abolish the induction of chemokines in MSCs, we cannot exclude that other factors than IL-1β can be released by metastatic breast cancer cells and could be involved in the stimulation of MSCs." (PMID 26362269, 2015).
Stroke (548 papers, 2006 to 2026). Sudden impairment of blood flow to a part of the brain due to occlusion or rupture of an artery to the brain. "The interleukin (IL)-1β–IL-6–C-reactive protein (CRP) axis is central in stroke pathophysiology and turned out to be associated with recurrent strokes, not only restricted to atherothrombotic events [30▪,31]." (PMID 41311168, 2026). "Clinical meta‐analyses and cohort datasets have demonstrated that elevated levels of Il6, Il1β, Cxcl2, and Cxcl10 are closely associated with poorer stroke prognosis." (PMID 40585759, 2025). "Patients with higher cholesterol, LDL, SBP, and DBP levels and lower HDL levels, together with the presence of IL-1β (rs16944) and IL-10 (rs1800896) polymorphisms, were more likely to develop stroke." (PMID 40369205, 2025). "IL-1β is associated with the inflammatory activity, including the accumulation of Aβ peptides, and has further been linked to stroke, AD, and multiple sclerosis." (PMID 40016149, 2025). "NLRP3 inflammasome can activate caspase-1 state to cleaved, which in turn exposes the N-terminal of GSDMD for pore formation in cell membrane and promotes secretions of IL-1β and IL-18, causing serious of outcomes in stroke." (PMID 40289983, 2025). "In a GWAS study of stroke and its subtypes, it has been confirmed that inflammatory factors, such as IL-1β, IL-12, and M-CSF, play a critical role in the onset of stroke and are closely associated with its occurrence." (PMID 39787159, 2025). "Canakinumab, a monoclonal antibody targeting IL-1β, has been shown to reduce the risk of myocardial infarction, cardiovascular death, and stroke in patients with coronary heart disease (CHD)." (PMID 41009650, 2025). "Previous studies reported that IL-1β levels are increased both in the plaque and plasma of patients with carotid vulnerable plaques, which is associated with higher risk of stroke recurrence." (PMID 36536168, 2024). "IL1-β plays a central role in mediating the inflammatory response following stroke, and preclinical studies demonstrate that increased IL1-β was associated with larger infarct size." (PMID 38802847, 2024). "Within 6 to 12 h after cerebral ischaemia, the levels of TNF-α, IL-1β and IL-6 are increased in stroke patients and are associated with more severe neurological symptoms and poorer outcomes." (PMID 39198723, 2024). "In the early stage post-stroke, M1 phenotype microglia are considered to cause damage to the surrounding neuronal cells by secreting pro-inflammatory factors (including IL-6, IL-1β, IFN-γ, TNF-α, IL-15, IL-18, and IL-23)." (PMID 37464832, 2023). "Although there are indications of a detrimental role of IL-1β, a study showed that an increased IL-1β concentration was linked with protection from stroke development in HbSS children with abnormal transcranial doppler (TCD)." (PMID 36969226, 2023). "We evaluated the associations of Malat1 expression with VitD level, and IL-1β on theperipheralblood of IS patients 0-24 h after stroke onset for the first time." (PMID 38974129, 2023). "IL-1β has been associated with exacerbation of injury in stroke and has been implicated in the pathogenic processes associated with a number of central nervous system disorders, while IL-6 and IL-10 have been found to be neuroprotective." (PMID 36969226, 2023). "IL-1β is a major inflammatory cytokine that has been associated with exacerbation of injury in stroke, but that was shown to exert both deleterious and protective functions in stroke." (PMID 36969226, 2023). "IL-1β is considered a pro-inflammatory cytokine whose effects depend on the haplotype, with some of them linked to the risk of stroke." (PMID 37762627, 2023). "The significant associations between VitD level, Malat1 expression, IL-1β, and NIHSSwithin the first hours after stroke will provide a better and deeper understandingof the role of Malat1 expression and the protective role of VitD in strokepathogenesis." (PMID 38974129, 2023).